MMP8 (matrix metallopeptidase 8)
Diseases named in the same sentence as MMP8 in open-access papers (continued):
Sharing a sentence is not in itself a finding about the gene and the disease.
squamous cell carcinoma (1 paper, 2019). A carcinoma arising from squamous epithelial cells. "Similarly, in squamous cell carcinoma (SCC) of the skin, the epithelial level of MMP8 was not useful in distinguishing chronic, non-malignant leg ulcers from SCC, nor to explain the aggressiveness of SCC in organ transplant recipients." (PMID 31514474, 2019).
tendinopathy (1 paper, 2013). "MMP2, MMP3, MMP8, ADAMTS2, ADAMTS4, ADAM12 and collagen type I expression were regulated in a similar manner in tendinopathy compared to the current study." (PMID 23830915, 2013).
tick-borne encephalitis (1 paper, 2025). Tick-borne encephalitis is caused by an arbovirus of the Flaviviridae family (tick-borne encephalitis virus, TBEV), transmitted principally by the bite of the Ixodes ricinus tick. "However, prior evidence suggests that serum MMP8 exhibits stronger predictive value for blood-brain barrier (BBB) disruption than CSF MMP8 in tick-borne encephalitis (TBE) patients." (PMID 41452925, 2025).
tongue (1 paper, 2008). "In this work, we provide evidence that collagenase-2 (MMP-8) is a protective factor in mobile tongue SCC." (PMID 18253113, 2008).
toxoplasmosis (1 paper, 2014). A parasitic disease contracted by the ingestion or fetal transmission of toxoplasma gondii. "In a mouse model of toxoplasmosis, in addition to inflammatory monocytes and neutrophils, CD4+ and CD8+ T lymphocytes where also important source of MMP-8 and MMP-10." (PMID 25393535, 2014).
tuberculous meningitis (1 paper, 2017). "We have previously reported compartmentalized inflammatory responses in HIV-infected patients with tuberculous meningitis (TBM), in cerebrospinal fluid (CSF) and plasma, with elevated CSF MMP-1, -7, and -10 in TBM-IRIS compared with non-IRIS controls, although MMP-8 was not studied." (PMID 28475709, 2017).
type 1 diabetes (1 paper, 2025). "This study evaluates the levels of MMP8, interleukin 8 (IL-8) and AGEs in GCF in type 1 diabetes with different glycemic levels compared to healthy controls." (PMID 40141192, 2025).
uterine cancer (1 paper, 2019). Primary or metastatic malignant neoplasm involving the uterine corpus and/or the cervix. "In uterine cancer, MMP8 was more abundant in tumor samples compared to normal tissue, but its level was not linked to any clinicopathological features such as tumor grade." (PMID 31514474, 2019).
Uterine leiomyoma (1 paper, 2019). The presence of a leiomyoma of the uterus. "The progesterone receptor modulator CDB-2914, induces MMP expression, including MMP8, in uterine leiomyoma cells, but MMP8 is not activated by this treatment and its role remains unclear." (PMID 31514474, 2019).
vaginal inflammation (1 paper, 2018). "A recent study demonstrated that proinflammatory cytokines EMMPRIN, MMP-8, and NGAL levels were significantly associated with PMNLs count in vaginal Gram stain samples where the vaginal inflammation was defined as >4 PMNLs /HPF." (PMID 30147292, 2018).
venous ulcer (1 paper, 2017). "MMP8 is frequently associated with venous ulcer healing; however, it may not intervene in venous wall restructuring." (PMID 29267209, 2017).
ventilator-associated pneumonia (1 paper, 2015). Serious INFLAMMATION of the LUNG in patients who required the use of PULMONARY VENTILATOR. "Although increased levels of MMP8 and MMP9 of bronchoalveolar lavage fluid in earlier studies have been associated with severe infectious conditions such as ventilator associated pneumonias,the exact role of MMPs in inflammatory diseases of the lung is not yet understood." (PMID 26656474, 2015).
ZIKV infection (1 paper, 2019). "Our most intriguing observation was that ZIKV infection led to a decreased level of MMP8 from the endothelial cells." (PMID 31249527, 2019).
tumor (158 papers, 1995 to 2026). "MACC1 expression was significantly associated with metastasis status and tumor stage, whereas MMP8 expression was associated with tumor localization." (PMID 42193101, 2026). "In multivariate analysis, tumor stage remained the only consistent independent prognostic factor, while MMP8 showed a modest independent association in a separate model." (PMID 42193101, 2026). "MMP-8 is a pleiotropic collagenase involved in angiogenesis that has been implicated in atherogenesis and tumor suppression." (PMID 41026534, 2025). "Overexpression of MMP‐8 in cancer cells is linked to decreased survival rates in patients with ovarian cancer and hepatocellular carcinoma, indicating its pro‐tumor effects." (PMID 39801760, 2025). "Both analysis of GEO datasets and results obtained from tissue homogenates demonstrated higher expression of YKL-40 and MMP-8 in tumor tissue compared with normal colon mucosa and a positive association between YKL-40 and MMP-8 expression in the tumor." (PMID 37185706, 2023). "MMP8-expressing cells are less invasive in vitro, systemic MMP8 expression decreases tumor size in mice and MMP8 blood levels are associated with lower lymph node metastasis rates." (PMID 38017545, 2023). "Various complementary studies delved into the underlying mechanisms that link MMP8 upregulation and the reported tumor-protective effects." (PMID 38017545, 2023). "Tumour-associated MMP-8-positive PMNs combined with a low CRP level associated with a better prognosis compared to the absence of PMNs and an elevated CRP level." (PMID 35328734, 2022). "According to our study, tumour-associated MMP-8-positive PMNs are an independent positive prognostic factor in the univariable analysis, but the multivariable analysis did not confirm this result." (PMID 35328734, 2022). "The presence of tumour-associated MMP-8-positive PMNs combined with a low CRP level also predicted a better survival." (PMID 35328734, 2022). "In the multivariable analysis, we detected no statistically significant survival advantage when considering tumour-associated MMP-8-positive PMNs as an independent prognostic factor." (PMID 35328734, 2022). "MMP8 itself is involved in tumor survival and mobility, its expression is associated with both pro and anti-tumor effects in different types of tumor environments." (PMID 33275641, 2020). "Increased malignancy was also evident from changes in tumor vascularity and immune cell infiltration in Mmp8-deficient mice that became apparent at later stages of the model." (PMID 25848906, 2015). "In CRC tissues, YKL-40 is associated with the expression of MMP8 and may be involved in the immunological properties of the tumor microenvironment." (PMID 38031100, 2023). "Indeed, a remarkably similar population of tumour-associated immature neutrophils (MMP8+ subtype) was identified by scRNAseq analysis and expressed genes associated with the early neutrotime signature." (PMID 37534829, 2023). "The anti-tumor properties of MMP-8 were first demonstrated in MMP-8-deficient mice." (PMID 35201460, 2021). "In addition, deletion of MMP8 in the MMTV-PyMT model caused an early tumor onset and increase incidence of lung metastasis." (PMID 34043703, 2021). "Whilst the molecular basis for this requires further experimentation it is interesting that MMP1 and MMP13 have been found to be upregulated in a variety of different tumours, including cervical, whilst MMP8 on the other hand has been associated with an anti-invasive effect in certain settings." (PMID 31116803, 2019). "Additionally, variating levels of MMPs, MMP8 included, can be visualized with tomography methods in breast cancer tumors in vivo (murine), offering a diagnostic tool to evaluate tumor progression and heterogeneity." (PMID 31514474, 2019).
tumor (continued). "An assemblage of systemic inflammatory markers and tumour-infiltrating immune cells were analysed, which enabled a more in-depth view of the relationships between serum MMP-8 levels and tumour associated inflammatory reactions than the analyses of a single marker." (PMID 29808017, 2018). "Despite the already aggressive nature of the MMTV-PyMT model, which leads to rapid, multifocal tumor formation in the mammary gland and a high frequency of lung metastasis, homozygous loss of MMP-8 further accelerated tumor onset, progression and lung surface metastasis formation." (PMID 25848906, 2015). "MMP8+ TANs were enriched for gene signatures associated with classical neutrophil properties including azurophil and gelatinase granules' secretion, neutrophil activation and phagocytosis, which have all been proposed as potential anti-tumour mechanisms and were termed immature TANs." (PMID 37534829, 2023). "In the later stages of tumor development (10 weeks of age), we found that while vascularization and neutrophil infiltration in tumors in wild-type animals had decreased overall compared to earlier lesions at 8 weeks, these parameters remained elevated in MMP-8 deficient animals." (PMID 25848906, 2015). "Data generated from our studies clearly demonstrated that Spry1KO led to the down-regulation of several MMPs, including MMP-2, MMP-3 and MMP-8, which have been recently explored as targets to hamper cancer angiogenesis and, in turn, tumor cell dissemination." (PMID 39953610, 2025). "Nevertheless, the secretion of other molecules implicated in the regulation of tumor angiogenesis in CM (e.g., MMP-2, MMP-3, MMP-8) were significantly reduced in Spry1KO Mel 593 clones." (PMID 39953610, 2025). "As the tumor progressed, pro-inflammatory neutrophils (i.e. Ccl3- and Mmp8+ neutrophils) infiltrated the TIME of the SC models, whereas angiogenic neutrophils (i.e. Myo1e+ neutrophils) remained the predominant type of immune cell in the TIME of the BOT models." (PMID 40899264, 2025). "Such N2‐polarized neutrophils aid in tumor progression by releasing neutrophil elastase (NE) and matrix metalloproteinases 8/9 (MMP8/9) for active ECM remodeling." (PMID 41346571, 2025). "In contrast, N2 TANs are generally pro-tumor and can promote tumor growth through elastase secretion while releasing MMP8, MMP9, and VEGF to facilitate metastasis and angiogenesis." (PMID 40724900, 2025). "The remaining genes were downregulated in all tumor groups, with the most pronounced changes observed for MMP8, MMP3, and MMP10." (PMID 38474106, 2024). "The expression of YKL-40 was significantly higher in CRC tumor tissue compared to healthy tissue and correlated with MMP-8, IL17A, and PD-L1 expression." (PMID 37185706, 2023). "Further, studies have shown that both MMP-8 and -9 have both tumor-promoting and -suppressing effects in cancers as well." (PMID 38275388, 2023). "Cluster 4 expressed MMP8, which is mainly produced by neutrophils that can either inhibit or promote tumor progression in certain cancers." (PMID 37158921, 2023). "We found significantly higher levels of YKL-40, PD-L1, MMP8, and IL-17 in the tumor in comparison to the margin tissue." (PMID 37185706, 2023). "In CRC tumor tissue, CHI3L1 is associated with the expression of MMP-8, IL17A, and PD-L1, thereby influencing the tumor microenvironment." (PMID 38003338, 2023). "According to reports, MMP8 is involved in the progression, metastasis, and invasion of cancer through its pro-cancer and anti-tumor functions." (PMID 38031100, 2023). "It would be beneficial to study if elevated levels of active MMP-8 and -9 in the mouth have tumor-promoting or -suppressing effects in HNC patients that would correlate with treatment success." (PMID 38275388, 2023).
tumor (continued). "We examined the prognostic value of MMP-8 immunoexpression in tumour tissue and the amount of MMP-8-positive polymorphonuclear cells (PMNs) in PDAC and their association with immune responses using C-reactive protein (CRP) as a marker of systemic inflammation." (PMID 35328734, 2022). "Further, MMP-8 was over-expressed in all tumor samples, as confirmed also by individual and mean densitometric values of tumor vs. normal skin samples, and the difference between the two groups was statistically significant (t-test; P < 0.05)." (PMID 36713871, 2022). "According to our findings, a high number of MMP-8-positive PMNs in a tumour together with low CRP levels indicate a better prognosis compared to the absence of PMNs and an elevated CRP level." (PMID 35328734, 2022). "According to the outcome prediction model, six valuable risk factors (direct lung injury, shock, tumor, BPI, MME and MMP8) were incorporated into the nomogram, which was used to predict the occurrence of ARDS in septic patients." (PMID 36685531, 2022). "MMP-8 expression in the tumour served as an independent positive prognostic factor (HR = 0.33; 95% CI 0.16–0.68; p = 0.003)." (PMID 35328734, 2022). "MMP8 is involved in tumor survival and morbidity since its expression has been associated with pro- and anti-inflammatory effects in different types of tumor microenvironments." (PMID 35359676, 2022). "Further studies led to the conclusion that some MMPs, such as MMP-8, have anti-tumor effects, therefore the broad-spectrum of MMPIs was shown to be counter-productive, ultimately resulting in tumor progression and overall intense toxicity." (PMID 36551666, 2022). "MMP-8 and -9 are collagenase MMPs that are expressed by fibroblasts and infiltrating inflammatory cells in addition to tumor cells." (PMID 36290656, 2022). "According to the outcome prediction model, six valuable risk factors (direct lung injury, shock, tumor, BPI, MME and MMP8) were incorporated into a nomogram, which was used to predict the onset of ARDS in septic patients." (PMID 36685531, 2022). "Here, by immunohistochemistry and western blotting analysis, we demonstrated overexpression of MMP-8/-13 along with a down-regulation of MMP-1, associated with a decrease in TIMP-3 levels in tumor compared with normal skin samples." (PMID 36713871, 2022). "Ablation of MMP8 in the MMTV-PyMT model accelerated tumor onset and increased incidence of lung metastasis." (PMID 33235291, 2021). "Additional experiments are needed to further characterize the function of FXYD5 in vivo and the cleavage by neutrophil or tumour-derived MMP8 should be considered in experimental settings." (PMID 34059618, 2021). "A six-gene risk score, the SCCHN TMI (SCCHN-tumor matrisome index: composed of MASP1, EGFL6, SFRP5, SPP1, MMP8 and P4HA1) was constructed and used to stratify patients into risk groups." (PMID 34830910, 2021). "In this study, we explored novel potential substrates of MMP8 to unravel the molecular basis for its tumour-protective effects in aggressive OTSCC." (PMID 34059618, 2021). "We mapped the substrates of MMP8 to elucidate its previously shown tumour-protective role in oral tongue squamous cell carcinoma (OTSCC)." (PMID 34059618, 2021). "MMPs lacking a transmembrane domain are expressed on the surface of other cells including MMP‐1 on keratinocytes, MMP‐2 on the surface of endothelial cells, fibroblasts, and tumor cells, and MMP‐8 and MMP‐9 on the surface of PMNs." (PMID 33656791, 2021). "Matrix metalloproteinases (MMPs) modify bioactive factors via selective processing or degradation resulting in tumour-promoting or tumour-suppressive effects, such as those by MMP8 in various cancers." (PMID 34059618, 2021). "Tumor-associated neutrophils (TANs) release neutrophil elastase (ELA2), collagenase (MMP8) and gelatinase B (MMP9), which contain in their granules." (PMID 33996815, 2021).
tumor (continued). "Depending on the MMP involved and the tissue site where a tumor is located, they can also have tumor-suppressive effects; an example of this is provided by MMP-8 and MMP-12, which are recognized as anti-tumor MMPs." (PMID 33419373, 2020). "Overexpression of MMP8 is significantly associated with higher clinical stage, overexpression of MMP11 is significantly associated with bigger tumor size, and low expression of MYB is significantly related to worse pathologic grade and metastasis." (PMID 32309437, 2020). "Since the tumor-protective effects were demonstrated in 2003, MMP8 has been regarded as an anti-target in MMP inhibitor development." (PMID 31514474, 2019). "Systemic MMP8 expression was found to decrease tumor size, hinder tumorigenesis and protect from metastasis formation." (PMID 31514474, 2019). "We aim to create an overview of the potential prognostic value of MMP8 in blood and tumor samples as well as highlight the effect of genetic changes in MMP8 for prognosis." (PMID 31514474, 2019). "Expression and genetic alterations of MMP8 can be used as a prognostic factor by examination of the tumor and serum/plasma." (PMID 31514474, 2019). "For instance, in syngeneic melanoma and the lung carcinoma mouse models, MMP-8 prevented metastasis formation by regulating tumor cell adhesion and invasion." (PMID 31010242, 2019). "Our aim was to evaluate serum levels and tumor expression of matrix metalloproteinase-8 (MMP-8) and tissue inhibitor of metalloproteinase-1 (TIMP-1) and to assess their prognostic role in HPV-positive and HPV-negative OPSCC." (PMID 31240326, 2019). "Yet in the SCC of oral (mobile) tongue (OTSCC), higher MMP8 in tumor favored better prognosis and lower mortality although very high and negative levels hinted towards shorter DFS." (PMID 31514474, 2019). "Analysis of MMP8, performed in a variety of different head and neck SCCs (HNSCCs), localized MMP8 protein to tumor cell islands, PMNs, plasma cells and fibroblasts." (PMID 31514474, 2019). "This phenomenon can partly be explained by different sources of MMP8 in the body, such as tumor cells and neutrophils." (PMID 31514474, 2019). "Serum MMP-8 negatively correlated with tumour-infiltrating mast cells (invasive margin: p = 0.005, tumour centre: p = 0.010)." (PMID 29808017, 2018). "We analysed the correlations between serum MMP-8 levels and the densities of six types of tumour-infiltrating immune cells." (PMID 29808017, 2018). "MMP-8 and -9 belong to the collagenase subgroup of MMPs being expressed – apart from tumor cells – also by fibroblasts and infiltrating inflammatory cells." (PMID 29929486, 2018). "Serum MMP-8 was also higher among those with the tumor located in the right side of the colon (P = 0.038)." (PMID 29929486, 2018). "The effect of altering MEC MMP-8 expression on tumour cell invasion was investigated in 2D and 3D organotypic models." (PMID 28330493, 2017). "This study aimed to address the role of MMP-8 in MECs and the impact of its loss on MEC phenotype and tumour-suppressor function." (PMID 28330493, 2017). "MMP-8 was identified as a tumour suppressor nearly a decade ago when the MMP-8 knock-out mouse was found to be more susceptible to skin tumuorigenesis as compared to a WT mouse." (PMID 28330493, 2017). "There was a significant decrease in tumour cell invasion only in the presence of MMP-8 WT transfected β6-1089 cells." (PMID 28330493, 2017). "This was further supported by enhanced transwell invasion for all tumour cells in the presence of N-1089 MMP-8 knock-down cells." (PMID 28330493, 2017). "On the contrary, MMP-8 has a confirmed protective role in tumor progression, and its inhibition should be avoided." (PMID 27782083, 2016). "The effect of MMP-8 ablation on tumor onset and growth was investigated in cohorts of Mmp8-wild-type, heterozygote and null female PyMT littermates." (PMID 25848906, 2015).